KRAS (KRas proto-oncogene, GTPase)
Diseases named in the same sentence as KRAS in open-access papers (continued):
Sharing a sentence is not in itself a finding about the gene and the disease.
lung cancer (continued). "The KRAS gene is often mutated in lung cancer, which can prevent binding of let-7b to the target site (preventing mRNA degradation), and downregulate let-7b through further downstream complications of upregulated KRAS." (PMID 35026982, 2022). "A significant portion (41.5%) of KRAS mutation positive lung cancer patients harbor low expression of ZNF24." (PMID 36457047, 2022). "While selective KRAS G12C and G13C inhibitors demonstrated some promise in lung cancer patients recently, these mutations however are present in less than 5% of CRCs." (PMID 35307764, 2022). "After treating organoids with MA for 72 h, calcein (viable cell dye) staining showed that MA significantly inhibited organoid spheroidization in a dose-dependent manner, indicating that MA inhibited the stemness of KRAS-mutated lung cancer cells." (PMID 36712673, 2022). "EGFR and ALK inhibitors have become the mainstays of treatment in lung cancer therapy, while in recent years a new class of drugs has been able to target the once “un-druggable” KRAS mutation." (PMID 36230484, 2022). "In the present study, we evaluated the efficacy of pan-EGFR inhibitors in a panel of 15 lung cancer cell lines associated with the KRAS mutations phenotype." (PMID 35887120, 2022). "The Kirsten rat sarcoma viral proto-oncogene (KRAS) is the most frequently mutated isoform (86%) and almost exclusively present in lung cancer." (PMID 35887862, 2022). "KRAS mutations are typically clonal, occur in early carcinogenesis, and are mutually exclusive with other mutations in lung cancer such as EGFR and ALK." (PMID 35877239, 2022). "Our results provide further evidence suggesting that AMPK mediates methuosis in lung cancer cells carrying KRAS mutation." (PMID 35806262, 2022). "The associations of responses and OS with KRAS mutation subtypes and comutations were analyzed in 87 KRAS-mutated lung cancer patients treated with ICIs." (PMID 36230855, 2022). "KRAS G12C mutations are frequently found in lung cancer due to G:C>T:A transversions associated with carcinogen-DNA adduct generated by the mutagens in tobacco smoke." (PMID 36012655, 2022). "Since KRAS-mutated NSCLC is typically smoking-related lung cancer, with more than 90% of patients having a history of smoking, it is more likely that such patients will respond to ICI treatment." (PMID 36741723, 2022). "The analysis of the Cox proportional hazards model from multiple databases illustrated that a high KRAS level is associated with lung cancer." (PMID 35563733, 2022). "HK2 plays a critical role in KRAS-dependent tumorigenesis in mouse lung cancer models, and in other cancers, with loss of HK2 attenuating tumor phenotypes and improving survival." (PMID 35410460, 2022). "We observed that the high-risk group had a higher KRAS mRNA level than the low-risk group, and the high-risk group presented worse OS outcomes in lung cancer, ovarian cancer, kidney cancer, colon cancer, and stomach cancer." (PMID 35563733, 2022). "The molecular and clinical features of KRAS-mutated lung cancer patients treated with immunotherapy have yet to be well characterized, and little information is known about resistance in these patients." (PMID 36230855, 2022). "Studies have shown that sotorasib (KRAS G12C inhibitors) bring effective antitumor activity in lung cancer patients with KRAS G12C mutation." (PMID 36456645, 2022). "Another subset of lung cancers (about 40%) have an oncogenic KRAS mutations indicating that driver mutations are, to some extent substitutable." (PMID 35061724, 2022).
lung cancer (continued). "Depending on the population and the series, the frequency of KRAS mutations in lung cancer patients is variable, identified in around 20% to 40% of lung adenocarcinomas and in around 5% to 7% of lung squamous cell lung carcinomas." (PMID 35406400, 2022). "Before the simulation, we updated our previously established in silico topology of a cancer signaling network by integrating frequent co-mutations from patients with KRAS-mutated lung cancer and modified it in a cancer cell line-specific way." (PMID 35565305, 2022). "Along the same line, primary resistance to PD-1 based therapies in KRAS-mutant lung cancer patients is mainly associated with LKB1 alterations in cancer cells." (PMID 36074553, 2022). "Activation of the RAS-MAPK signaling pathway is a common mechanism of osimertinib resistance in KRAS-mutated lung cancer cells and EGFR-TKI-resistant cells." (PMID 36712673, 2022). "Adagrasib is the second-most selective KRAS inhibitor currently being reviewed by the FDA for accelerated approval for patients with lung cancer who harbor the KRAS c.34G > T (p.G12C) mutation." (PMID 36077640, 2022). "Our study showed that the incidence of SMAD4 co-mutations in KRAS-mutant lung-cancer patients was 5.5%, higher than in the NSCLC population at 2.5%." (PMID 35887766, 2022). "The KRAS-pathway is known to be involved in cellular proliferation associated with colon, pancreatic, and lung cancer and has previously been shown to have an influence on HIF1A translational regulation within hypoxia." (PMID 35326510, 2022). "It as been recently shown that LKB1 loss is associated with decreased STING expression in KRAS mutant lung cancer resulting in impaired T cell recruitment and antitumor activities." (PMID 36359882, 2022). "In a phase 2 trial for patients with lung cancer harboring the KRAS G12C mutation, sotorasib treatment resulted in an overall response rate (ORR) of 37%." (PMID 36088851, 2022). "Remarkably, among this specimen, there were a total of 825 mutation sites in 684 mutated genes, of which only one KRAS gene (non–small cell lung cancer OMIM ID: 211980) was certified as pathogenic by ClinVar." (PMID 36128740, 2022). "It was previously reported that the primary mechanism underlying XPO1 inhibitor sensitivity of KRAS-mutant lung cancer cell lines was intolerance to nuclear IκBα accumulation, with consequent inhibition of NF-κB signaling." (PMID 35573474, 2022). "Although neglected until few years ago, the clinical role of KRAS mutations has now gained a central role in the oncologic management of lung cancer patients." (PMID 36077640, 2022). "FDA has recently granted approval to sotorasib for KRAS G12C–mutated non–small cell lung cancer (NSCLC)." (PMID 35573474, 2022). "For instance, some reports have shown that LDH expression and activity are increased in KRAS mutated lung cancers and increased GLUT expression in KRAS mutated cells that amplified glycolysis rate in pancreatic cancer." (PMID 36238683, 2022). "KRAS mutation is common in some solid tumors (e.g., pancreatic cancer, lung cancer, and colon cancer), which leads to a disappointing prognosis." (PMID 36452227, 2022). "While the link between lung cancer and KRAS mutation (mt KRAS) is a widely discussed topic in research, attempts to develop targeted therapy are reported to be elusive." (PMID 35877239, 2022). "Studies found that a significant amount of lung cancer patients are cigarette smokers, and KRAS mutation is also frequent in adenocarcinomas." (PMID 35409064, 2022). "In this regard, many studies and initiatives are currently ongoing to improve the different aspects related to KRAS-mutated lung cancers." (PMID 35406400, 2022). "We found that around 41.5% of KRAS mutation positive lung cancer patients harbor low expression of ZNF24 (designated Zno/K* patients)." (PMID 36457047, 2022).
lung cancer (continued). "KRAS is the most frequently mutated oncogene in lung carcinomas, accounting for 25% of total incidence, with half of them being KRASG12C mutations." (PMID 35053550, 2022). "In lung carcinoma cell lines, apoptosis induction by Dinaciclib was, however, stronger in the presence of a KRAS mutation." (PMID 35326726, 2022). "The KRAS gene is found to be mutated in various types of tumors, such as pancreatic carcinoma (over 80%), colon carcinoma (40–50%), lung carcinoma (30–50%), and others." (PMID 35409064, 2022). "Recently, sotorasib (AMG510), a compound directly targeted to KRAS with the G12C mutation, was shown to cause the regression of KRAS G12C lung carcinoma." (PMID 35785187, 2022). "Christopher Marshall’s group used conditional knockout of the RAL alleles in a KRAS-driven mouse model of lung carcinoma." (PMID 35626682, 2022). "This epigenetic reprogramming indicates new therapeutic approaches to tumorigenesis, especially for the lung cancer with dual KRAS mutation/LKB1 loss." (PMID 34016959, 2021). "Mutations in codons 12, 13, and 61 of KRAS have oncogenic potential, and KrasG12X mutations are the most abundant mutation types in lung cancer patients." (PMID 34635780, 2021). "Non-small cell lung cancer (NSCLC) is the most common type of lung cancer accounting for about 85% of all lung cancer cases and KRAS mutations are the most frequent alteration in these cancers." (PMID 33801965, 2021). "Based on these clinical observations, we used a mouse model with a lung-specific expression of the KrasG12D mutation to test BLT2 as an alternative target for KRAS-driven lung cancer." (PMID 34635780, 2021). "Another retrospective study found similar activity of immunotherapeutic agents in KRAS mutated compared to KRAS wild-type lung cancer patients." (PMID 33777798, 2021). "Further efforts are dedicated to elucidating the impact of different KRAS mutation subtypes in lung cancer patients on treatment efficacy." (PMID 35070984, 2021). "ALK rearrangements were shown to be associated with increased VTE risks in patients diagnosed with non-small lung cancer, while there was no significant relation observed between VTE risks and EGFR or KRAS mutations in lung cancer patients." (PMID 33996610, 2021). "FOSL1 can regulate gene expression induced by KRAS mutation, and thus control cell proliferation and survival, and predicts a poor prognosis in lung cancer." (PMID 34430085, 2021). "This limited efficacy underlies a relevant molecular heterogeneity among KRAS-mutant lung cancer, with such an innate or acquired resistance to targeted therapy, requiring further investigations." (PMID 35004317, 2021). "Another neutrophil chemoattractant, CXCL1, is also upregulated by KRAS mutations, and is involved in the development of lung cancer." (PMID 34885068, 2021). "KRAS mutations causes the most deadliest cancers (lung cancer, colorectal cancer, and pancreatic cancer)." (PMID 34830024, 2021). "We reasoned that CanDI enables us to rapidly search functional genomics data for genes that are conditionally essential in lung cancer cells driven by KRAS and EGFR mutations." (PMID 34663427, 2021). "Its expression was found to be associated with Ki-67 expression and KRAS mutation in resect lung cancer." (PMID 34227915, 2021). "ARS-583 inhibits downstream MAPK/PI3K signaling across the group of cell lines and directly inhibits the treatment of patients with the KRAS G12C mutation, which comprises 20% of lung cancers." (PMID 34830757, 2021). "KRAS mutations are frequent genomic events in lung cancer, especially in Non-Small Cell Lung Cancers (NSCLC)." (PMID 34573384, 2021). "Recently, immune checkpoint blockage through targeting programmed death-ligand 1 (PD-L1) and by its receptor programmed death-1 (PD-1), has changed the treatment paradigm for lung cancer patients, especially for those harboring a KRAS mutation." (PMID 34073318, 2021).
lung cancer (continued). "Interleukin-6 (IL-6) is a proinflammatory cytokine that has been implicated in the progression of lung cancers, including KRAS-driven lung cancer." (PMID 34635780, 2021). "The results are consistent with the previous findings that G12C is the most common mutation, while G12S only accounts for less than 1% of the KRAS mutations in lung cancer." (PMID 33467412, 2021). "Adenocarcinoma, the major form of lung cancer, is associated with activating mutations in the oncogenic small GTPase KRAS." (PMID 35071236, 2021). "In the case of NSCLC, the KRAS mutation has emerged as a clinical challenge to be addressed, as KRAS-mutant lung cancer often causes complications in systemic anti-cancer drug therapy." (PMID 32530390, 2021). "We conclude that loss of LKB1 promotes ALKBH5 transcription by a DNA methylation mechanism, reduces m6A modification, and increases the stability of m6A target oncogenes, thus contributing to aggressive phenotypes of KRAS-mutated lung cancer." (PMID 34016959, 2021). "Specifically, KRAS transcript variants v13, v14, v15, v16, v17 and v19 were found to be highly expressed in lung cancer." (PMID 34948093, 2021). "In the past decade, two important sources of mutations in lung cancer have been discovered, namely Kirsten RAt Sarcoma 2 viral oncogene homolog (KRAS) and epidermal growth factor receptor (EGFR) mutations." (PMID 32530390, 2021). "Meanwhile, anti-angiogenic drugs have shown differential efficacy for different subtypes of KRAS mutated lung cancer." (PMID 35070984, 2021). "As to other therapeutics developed targeting mutant KRAS, the FDA granted sotorasib, a KRAS G12C small molecule inhibitor priority review status in 2021 for the treatment of non–small cell lung cancer patients with KRAS G12C mutation." (PMID 33804856, 2021). "Mutation of KRAS gene in lung cancer is more frequent than NRAS and HRAS and is often associated with poor prognosis and worse therapeutic outcome." (PMID 33549031, 2021). "Several researches show that KRAS mutation is the most common genetic alteration type, and it occurs in approximately 10–25% of lung cancer in Western and Asia countries." (PMID 33435990, 2021). "The expression data also showed 1.7-fold up regulation of MUC5AC in radiation resistant cells, and functionally it has been linked to focal adhesion kinase (FAK) phosphorylation, and lung cancer proliferation, and KRAS mutated aggressive lung cancer." (PMID 34762666, 2021). "Focusing on lung cancer, in humans oncogenic KRAS mutations have been detected in premalignant lesions as well as in multiple regions within the same tumor, indicative of an early origin." (PMID 33998997, 2021). "KRAS mutations in lung cancers are more common in AA patients than CA patients that make mTOR a potential therapeutic target for KRAS-mutant lung cancer." (PMID 33996789, 2021). "A total of 7 lung cancer patients had insufficient tumor material for mutational analysis, where one patient had a detectable KRAS mutation in cfDNA." (PMID 34217228, 2021). "In KRAS-mutated lung cancer, there is a synergic effect of STK11/LKB1 and KEAP1 loss: STK11/LKB1 loss results in an increased level of ROS and high redox stress with an inability to maintain ATP levels." (PMID 34831355, 2021). "These mutations were identified in lung cancer almost three decades ago and have been traditionally associated with a poor prognosis compared to KRAS wild type tumors." (PMID 33807876, 2021). "Recent advances in understanding the molecular pathogenesis of lung cancer with oncogenic KRAS have enabled the development of drugs, yet mutated KRAS remains undruggable." (PMID 33830081, 2021).
lung cancer (continued). "Consistent with this notion, two classical ferroptosis small molecule inducers, erastin and RSL3, are lethal chemical agents in KRAS mutation-containing tumor cells, including various lung cancer cells (e.g., Calu-1)." (PMID 34742351, 2021). "KRAS G12C and G12D are the most common types of mutations in lung cancer patients, accounting for 33.6% and 23.9% of total KRAS mutations, respectively." (PMID 35070984, 2021). "Patients with adenosquamous carcinoma (14.29%) and patients with stage IIB lung cancer (11.11%) had a higher E2 mutation rate in the KRAS gene." (PMID 34217313, 2021). "Meanwhile, among KRAS mutated lung cancer patients, OS was longer and statistically significant for adenocarcinoma patients compared with squamous carcinoma patients (22.7 vs. 11.5 months; p = 0.051)." (PMID 35070984, 2021). "KRAS 12C and KRAS 12S mutations were more commonly observed in lung cancer, whereas G12D mutation was frequently found in pancreatic cancer." (PMID 33467412, 2021). "Collectively, co-mutations of LKB1 and/or KEAP1 with KRAS in lung cancer are associated with KRAS independency through a rewiring of metabolic processes." (PMID 34680229, 2021). "KRAS mutations (especially KRAS-G12C) are commonly found in lung cancer and are associated with poor prognosis and therapy resistance." (PMID 34742351, 2021). "The special relationship carried by KRAS-driven lung cancers with SMARCA4 loss was studied by some research groups." (PMID 34440689, 2021). "For instance, in lung cancer, source-level paired aberrations involving KRAS were most strongly associated with smoking, whereas those involving EGRF showed an opposite trend, consistent with well-established patterns." (PMID 34115745, 2021). "LKB1-inactivated KRAS mutant lung cancers harbor co-mutations in KEAP1 and/or significant co-occurrences of copy number loss in STK11/LKB1 and KEAP1 due to the chromosomal proximity of these genes." (PMID 34680229, 2021). "The activating KRAS mutations are found in numerous malignancies with a frequency of 90% in pancreatic cancer, 35% in lung cancer, and 30%–60% in colon cancer." (PMID 33467412, 2021). "Of the three RAS family members, KRAS is the most frequently mutated form in pancreatic, colorectal, and lung cancer." (PMID 33562401, 2021). "Lung cancer is a complex disease associated with gene mutations, particularly mutations of Kirsten Rat Sarcoma Viral Oncogene Homolog (KRAS) and epidermal growth factor receptor (EGFR)." (PMID 34830377, 2021). "Mutant KRAS causes a persistent activation of the PERK/p-eIF2α pathway, which accounts for the higher susceptibility of mutant than WT KRAS lung cancer cells to ISR inhibition." (PMID 34330898, 2021). "Based on this, a KRAS gene mutation in A549 EGFR‐wild‐type lung cancer cells actively promotes over‐phosphorylated EGFR‐AKT levels, keeping its over‐activated level even when using EGFR‐TKIs treatment." (PMID 33433063, 2021). "Mechanistically, we found that lung cancer cells harboring the KRAS mutation exhibited a higher level of programmed death ligand 1 (PD-L1)." (PMID 34073318, 2021). "Based on this, the authors concluded that in KRAS-driven lung cancer, Stk11 mutations were essential for tumor progression." (PMID 34781949, 2021). "Given that KRAS mutations appear to be an early event in smoke-related lung cancer 6, a KRAS-mutated human lung cancer cell line, A549 (G12S), was utilized to test the anti-stemness effect of MPS peptide in vivo." (PMID 33754052, 2021).